INS (insulin)
Diseases named in the same sentence as INS in open-access papers (continued):
Sharing a sentence is not in itself a finding about the gene and the disease.
diabetes (continued). "Diabetes can be caused either by the incapability of the body to produce enough insulin or by the resistance of the body to the insulin." (PMID 35808386, 2022). "Diabetes mellitus is a metabolic disease caused by defective insulin secretion and/or insulin action." (PMID 35030973, 2022). "Inability to either produce enough insulin or have proper insulin-based signaling causes diabetes mellitus, which is characterized by high blood glucose levels." (PMID 36297679, 2022). "Significant factors affecting the risk for adolescent diabetes in both sexes were higher BMI, fasting plasma glucose, hemoglobin A1c, and insulin." (PMID 36010139, 2022). "In insulin-dependent diabetes mellitus, islet cells can secrete a certain amount of insulin, but the sensitivity of insulin is reduced, resulting in relative insulin deficiency in the body and causing metabolic disorders in the body and hyperglycemia." (PMID 36407115, 2022). "Type 1 diabetes mellitus is a chronic autoimmune disease characterized by the loss of insulin-producing pancreatic β-cells." (PMID 35783304, 2022). "Several switch genes, including AKT3, LAMA2, ADCY1, RAB3A, RAPGEF4, and ABCC8, have been implicated in insulin signaling and diabetes." (PMID 36389068, 2022). "In summary, we provide evidence that Glrx5 is regulated by FFA in type 2 diabetes mellitus and is linked to mitochondrial dysfunction and blunted insulin secretion." (PMID 35453472, 2022). "The consequences of proinsulin folding mutations were also demonstrated through dozens of human INS gene mutations that result in the syndrome known as mutant INS-gene-induced diabetes of youth (MIDY)." (PMID 35204835, 2022). "Both in our chemical model of STZ and in diabetes, weight loss is due to the fact that when beta-pancreatic cells die, there is insufficient production of insulin to capture glucose in the different tissues and maintain homeostasis." (PMID 36432781, 2022). "Impaired insulin signaling increases risk of Alzheimer’s disease, cognitive disabilities in diabetes mellitus whereas intranasal administration of insulin improves hippocampal-dependent memory function." (PMID 35264925, 2022). "A 10-year follow-up analysis of the UK Prospective Diabetes Study demonstrated that intensive glucose control with SU or insulin was associated with a significantly lower risk of macrovascular complications." (PMID 36429732, 2022). "In return, serum levels of triglyceride was associated with insulin action in non-insulin-dependent diabetes mellitus populations." (PMID 35260102, 2022). "In fact, each of the module components has been implicated with insulin, risk of diabetes or both in some manner (ADAM17, ATL2, MGP, SPLC2, N-methylproline, 3-methylhistidine)." (PMID 36329547, 2022). "The increase of free fatty acids caused by obesity and the rise of blood glucose caused by diabetes are both closely related to IR, and impairment of the insulin signaling pathway, a consequence of skeletal muscle IR, also leads to muscle atrophy." (PMID 36232938, 2022). "Diabetes mellitus (DM) is a chronic condition associated with raised levels of blood glucose due to the body cannot produce any or enough insulin hormone or cannot be effectively utilized the produced insulin by the body." (PMID 35895700, 2022). "Type 2 diabetes mellitus is caused by a variety of factors, one of which is a high-fat diet that leads to decreased insulin sensitivity and, consequently, insulin resistance." (PMID 36424928, 2022). "Diabetes mellitus is a metabolic disease caused by long-term hyperglycemia due to insufficient insulin secretion and insulin dysfunction." (PMID 36091757, 2022). "Mutations in the INS gene can cause various types of diabetes, including neonatal diabetes mellitus, maturity-onset diabetes of the young, and type I diabetes (especially antibody-negative type I diabetes)." (PMID 36686471, 2022).
diabetes (continued). "In the Akita mice model of disease, the mice suffer from insufficient insulin production secondary to β-cell loss, reaching toxic gain-of-function, ER stress with apoptotic pathway activation, and frank diabetes within 4 to 5 weeks after birth." (PMID 35806376, 2022). "The loss of functional β cell mass, as defined by insulin secretory capacity and β cell number, is the key defining feature of diabetes." (PMID 35298439, 2022). "Diabetes mellitus, commonly known as diabetes, is a set of metabolic disorders characterized by hyperglycaemia related to a deficiency in insulin secretion, insulin action or both." (PMID 36671612, 2022). "Diabetes is still one of the most threatening diseases to human health, and is mainly attributed to a low level, or absolute deficiency, of insulin, the principle hypoglycaemic hormone secreted by islet β cells." (PMID 34935260, 2022). "Recently, an exacerbation and aggravation of insulin resistance in sαKL deficiency was reported in patients with type 2 diabetes mellitus, while overexpression of sαKL was associated with increased insulin sensitivity." (PMID 35279809, 2022). "Diabetes is a disease caused by decreased insulin action which reduces the uptake and metabolization of glucose by cells." (PMID 36291290, 2022). "In terms of an excessive energy state, such as in patients with obesity or diabetes who have an impaired ability to degrade BCAAs, BCAAs and related metabolites accumulate in circulation to reduce insulin sensitivity and cause insulin resistance." (PMID 36219347, 2022). "Type 1 diabetes mellitus (T1DM) is a chronic disease represented by insulin-causing pancreatic β-cell disruption and hyperglycemia." (PMID 35978645, 2022). "Diabetes mellitus (DM) is a chronic metabolic disorder characterized by a high level of blood glucose resulting from a relative or absolute deficiency of insulin action." (PMID 35208957, 2022). "Unfortunately, the final consequences of a deficiency in PDX1 function are manifested in impaired insulin secretion and the development of diabetes mellitus." (PMID 35054822, 2022). "Diabetes is the most common endocrine and metabolic disease caused by absolute or insufficient insulin secretion." (PMID 35855056, 2022). "IGFBP1 has previously been linked to diabetes/insulin regulation, as lower circulating levels of IGFBP1 have been associated with impaired glucose tolerance, insulin resistance, diabetes, and cardiovascular diseases in mouse models." (PMID 36287121, 2022). "The role of miRNAs involved in neurodegeneration has emerged as a major focus of interest in recent years, and growing evidence highlights the relationship between AD and diabetes, and their association with dysregulation of insulin signaling." (PMID 35204710, 2022). "Loss of β cell FIT2 and LDs reduces insulin secretion, increases intracellular ceramides, stimulates ER stress, and exacerbates diet-induced diabetes in mice." (PMID 35254894, 2022). "Diabetes mellitus (DM) is a chronic metabolic disease characterized by hyperglycemia, which results from carbohydrate metabolic disorders associated with impaired insulin production (type 1) or developed insulin resistance (type 2)." (PMID 35204264, 2022). "The major pathogenic factors underlying diabetes are insulin (INS) resistance and β-cell dysfunction, which result in high blood glucose levels." (PMID 36119371, 2022). "Fumarase was predicted to be negatively related to insulin secretion; mice with fumarase-deficient β-cells developed diabetes, suggesting that proper regulation of the β-cell GSIS system is dependent on proper function of the fum reaction." (PMID 36251711, 2022). "Metabolic diseases such as obesity and diabetes are associated with low-grade inflammation, characterized by macrophage recruitment in different tissues, which contribute to alteration in insulin sensitivity and β-cell function." (PMID 36058931, 2022).
diabetes (continued). "Insulin often at high doses is frequently required to manage hyperglycaemia associated with severe SARS-CoV-2 infection in people with diabetes." (PMID 35256883, 2022). "On the other hand, hyperglycemia can occur as an effect of some pharmacological treatment (SSAs), surgery (pancreatectomy with subsequent iatrogenic diabetes), or tumor mass, causing a reduction in insulin secretion." (PMID 36139562, 2022). "Insufficient insulin release or insulin loss in target tissues can also easily lead to the occurrence of diabetes." (PMID 36139080, 2022). "Although elevated blood glucose levels are the defining feature of diabetes mellitus, multiple biochemicals alter the metabolism of fats and amino acids and are associated with impaired insulin action, obesity, and BCAA catabolic enzymatic activity." (PMID 36402758, 2022). "On one hand, sustained impaired insulin secretion will cause hyperglycemia and, eventually, diabetes." (PMID 35457000, 2022). "After silencing the PDX-1 gene in neonatal mouse islet β cells, insulin secretion is defective, causing impaired glucose tolerance and diabetes in adulthood." (PMID 36551213, 2022). "Diabetes is also characterized by abnormalities ranging from IR to absolute deficiency of insulin (type 1 diabetes) or abnormalities in the receptor protein itself post-transcription/translation/translation (type 2 diabetes)." (PMID 35955522, 2022). "This confirmed that the generated IPCs effectively secreted insulin which in turn succeeded in reversing the hyperglycemic state caused by diabetes." (PMID 35674918, 2022). "Type 2 diabetes mellitus is caused by relatively increased insulin resistance due to various causal factors such as health habits, even though insulin-secreting function remains partially." (PMID 36246911, 2022). "Diabetes is caused by either insufficient insulin production by the pancreas or an insufficient insulin response by the body's cells." (PMID 35875742, 2022). "Diabetes is a chronic disease caused by the defective insulin secretion in the body, resulting in abnormal metabolism with a continuous increase in blood sugar." (PMID 35178452, 2022). "Diabetes mellitus (DM) is a group of metabolic disorders with the result of deficiency or ineffectiveness of insulin featuring hyperglycemia." (PMID 36325365, 2022). "It is widely acknowledged that an absolute or relative deficiency caused by impaired insulin secretion or other factors can lead to diabetes." (PMID 36188222, 2022). "Diabetes mellitus (DM) is a chronic disease caused by the relative or absolute lack of insulin or the decreased sensitivity of target cells to insulin, which causes disorders of glucose, lipid, and protein metabolism." (PMID 36479195, 2022). "We excluded underlying diabetes mellitus, the use of insulin or oral anti-diabetic medications, and organ failure." (PMID 35758364, 2022). "Further research into the role of ceramides and mechanisms underlying GDM and diabetes development—especially in the pathophysiology of β-cells dysfunction and insulin resistance—is required." (PMID 35054078, 2022). "For example, indole propionic acid is associated with insulin sensitivity and appears to reduce the risk of diabetes." (PMID 36219347, 2022). "Diabetes has become a worldwide epidemic disease that is characterized by sustained hyperglycaemia caused by the improper function or diminished secretion of insulin." (PMID 35850665, 2022). "Type 2 diabetes mellitus (T2DM) is a metabolic disease caused by either inadequate production of insulin or an improper response to insulin." (PMID 36151544, 2022). "The results indicated that APE alleviated diabetes‐associated pancreato‐hepatorenal dysfunction by decreasing oxidative stress, glucose, and insulin sensitivity in NICO/STZ‐induced diabetic rats." (PMID 35432973, 2022). "Diabetes mellitus (DM) is caused by impaired insulin secretion, insulin resistance, or both and leads to high blood glucose levels (hyperglycemia)." (PMID 36432144, 2022).
diabetes (continued). "For example, module 67 can be placed in the context of insulin secretion and diabetes, with many of its components associated with diabetes risk." (PMID 36329547, 2022). "Genome-wide association studies have shown that most T2D risk loci are involved in regulating insulin secretion, suggesting a critical role for β-cells in driving diabetes risk." (PMID 35156417, 2022). "Patients with a mutation in a syndromic gene were more likely to be insulin treated (71% vs 39%, P<0.001) and less likely to have a parent affected with diabetes (53% vs 76%, P=0.001)." (PMID 34789499, 2022). "As diabetes results from the absolute or relative deficiency of insulin secretion from pancreatic β cells, possible methods to efficiently generate surrogate β cells have attracted a lot of efforts." (PMID 36496541, 2022). "In contrast, we have recently reported that both Cer-16 and its longer chain counterparts are associated with higher risk of incident diabetes, as well as with elevated fasting insulin and glucose levels." (PMID 36042511, 2022). "Patients affected by COVID-19 and diabetes mellitus type 2 treated with insulin are at increased risk of developing severe/critical complications or dying." (PMID 36079820, 2022). "Diabetes mellitus (DM) is a chronic disease caused by defective insulin action, defective insulin secretion, or both, usually manifesting as hyperglycemia." (PMID 35845783, 2022). "Insulin resistance, serum insulin levels, and oxidative stress are risk factors for several Mets components, including diabetes, hypertension, cardiovascular, and NAFLD." (PMID 36558967, 2022). "In our analysis, in the subgroup of new users of GLP-1RA and SGLT-2i treated with insulin in the previous 12 months, likely at a more advanced stage of diabetes, both cohorts displayed a similar risk of CV events occurrence." (PMID 35999556, 2022). "These chemicals can induce pro-inflammatory cytokines, decrease insulin secretion, and consequently increase the risk of diabetes and metabolic syndrome." (PMID 36274164, 2022). "Diabetes is a group of metabolic diseases characterised by chronic hyperglycaemia caused by multiple causes, which is caused by insulin secretion and/or utilisation defects." (PMID 35067136, 2022). "Insulin is used to treat diabetes which affected 537 million adults worldwide and caused 6.7 million deaths in 2021." (PMID 36559303, 2022). "Diabetes (diabetes mellitus) is a metabolic disorder caused by defective insulin secretion or insulin resistance, or both, resulting in chronic hyperglycemia (elevated plasma glucose levels) with glucose, lipid, and protein metabolic dysfunctions." (PMID 36551260, 2022). "In contrast, multiple factors were associated with leptin and insulin, including maternal diabetes, maternal BMI and infant’s birth weight." (PMID 35197933, 2022). "This can be explained by that apelin regulates insulin sensitivity and enhances brown adipogenesis in different tissues associated with diabetes." (PMID 35610700, 2022). "The activation of AhR impairs glucose metabolism, glucose tolerance, and insulin levels, thus increasing the risk of developing diabetes mellitus." (PMID 35268815, 2022). "Diabetes mellitus is often associated with paradoxical postprandial hyperglucagonemia; like insulin, amylin was shown to inhibit glucagon release, which therefore generates a preference for glucose accretion via meal-related glucose over endogenous stores." (PMID 35456307, 2022). "The majority of the selected research aims to solve a diabetes management problem (e.g., blood glucose prediction, early detection of risk events, and the automatic adjustment of insulin doses, etc.)." (PMID 35270989, 2022). "In the case of diabetes, cholesterol has been found to be accumulated within pancreatic β-cells, causing a decrease in insulin secretion." (PMID 36232867, 2022).
diabetes (continued). "Further reduced energy expenditure along with diminished insulin secretion and decreased insulin sensitivity increase the risk of diabetes in addition to aging." (PMID 35831938, 2022). "Upon tamoxifen induction of transgene expression, NDM mice rapidly developed severe diabetes followed by an unexpected loss of insulin content, decreased proinsulin processing and increased proinsulin at 2-weeks of diabetes." (PMID 35180212, 2022). "Since the ageing process is associated with reduced insulin sensitivity and type 2 diabetes mellitus, we assessed aspects of glucose metabolism in both young and old male WT and 11β-HSD1 KO mice." (PMID 36205523, 2022). "Diabetes includes a group of metabolic diseases characterized by chronic hyperglycemia due to a deficit in insulin secretion, deficient insulin action, or both." (PMID 36612540, 2022). "In our study, seven children with INS gene mutations had diabetes onset before 6 months of age whilst three were diagnosed between 6 months and 12 months." (PMID 35518939, 2022). "Adiponectin has been implicated in metabolic syndrome, with reduced levels in insulin resistant states and obesity-related syndromes such as hypertension and type 2 diabetes mellitus." (PMID 35544473, 2022). "This is not surprising since obesity is known to be associated with type 1 and type 2 diabetes mellitus, of which the latter is accompanied with decreased insulin production and peripheral insulin resistance subsequently leading to hyperglycemia." (PMID 35625491, 2022). "Diabetes mellitus (DM) is a metabolic disease characterized by high blood glucose due to insulin secretion deficiency or biological function impairment." (PMID 35774140, 2022). "Inherited or acquired deficient production of insulin or ineffectiveness of the insulin produced by the pancreas causes diabetes mellitus." (PMID 35607491, 2022). "Similar associations between diabetes and impaired hand dexterity have been reported in patients with diabetic neuropathy and, in especially the older, insulin-treated, patients with type 2 diabetes." (PMID 36171358, 2022). "The aging process in diabetes is associated with alterations in glucose metabolism, including both relative insulin resistance and islet cell dysfunction, thus leading to impaired glucose intolerance and/or postprandial hyperglycemia." (PMID 36359275, 2022). "This was a cross-sectional study using a self-administered instrument to gain insight into insulin needle disposal practices among patients with diabetes and to explore factors associated with safe sharps disposal practices." (PMID 36568796, 2022). "Research is needed to assess if physical activity interventions can improve β-cell function and insulin sensitivity to reduce risk of diabetes and delay progression of diabetes in SSA." (PMID 35992098, 2022). "We found that male offspring are more susceptible than females to diabetes risk in adulthood, possibly due to altered metabolic regulations of insulin, ghrelin, and glucagon during their early life." (PMID 36109770, 2022). "Serum Mg levels were also negatively associated with BMI and diabetes components such as fasting blood glucose and insulin levels, and glycated hemoglobin (HbA1c) as well as the Homeostatic Model Assessment for Insulin Resistance (HOMA-IR)." (PMID 35565682, 2022). "T1DM, also known as “insulin-dependent diabetes mellitus”, is caused by autoimmune destruction of insulin-producing β-cells in the patient’s pancreas and manifests as an absolute deficiency of insulin." (PMID 36147580, 2022). "As individuals with prevalent diabetes are known to have lower mtDNA-CN and type 2 diabetes is a disease primarily characterized by decreased insulin sensitivity, we re-examined this association after adjusting insulin sensitivity for diabetes status." (PMID 35849594, 2022). "Diabetes mellitus can be caused either by the insufficient secretion of insulin (Type 1) or/and by development of insulin resistance (Type 2)." (PMID 35736019, 2022).